EGFR (epidermal growth factor receptor)
Diseases named in the same sentence as EGFR in open-access papers (continued):
Sharing a sentence is not in itself a finding about the gene and the disease.
tumor (continued). "Collectively, the expression of Pgp and Hif-1α was elevated in the perimeter of tumors established from hypoxic cells relative to the core while the perimeter of tumors established from normoxic cells had lower expression of EGFR and higher expression of GLUT-1 relative to the tumor core." (PMID 21320311, 2011). "EGFR is particularly important in the pathogenesis of squamous cell carcinoma of the head and neck (SCCHN), with reported overexpression in approximately 90% of tumours." (PMID 21829197, 2011). "But for anti-EGFR mAbs, to our knowledge, there are no clinical data showing an enhancement of anti-tumor cellular immune responses as result of a passive immunotherapy." (PMID 24212794, 2011). "Thus, the synergistic effect was attributed to a double action of the anti-EGFR directly on tumour cells and of the anti-VEGFR on the tumour vascular component." (PMID 21504579, 2011). "Because tumour material was not available from all lesions, the EGFR status in 11C-erlotinib accumulating and non-accumulating tumour lesions is not known." (PMID 22095231, 2011). "Researchers have been investigating whether inhibiting both the EGFR and PTGS2 (COX-2) signaling pathways at lower doses could yield additive effects on blocking tumor growth and the spread of metastatic disease." (PMID 24213116, 2011). "Analysis of consecutive sections clearly demonstrated Oct4 and Nanog expression in tumor cells with EGFR gene amplification as well as in other tumor cells and other tumor samples without EGFR gene amplification." (PMID 21483788, 2011). "Also, Immunohistochemistry (IHC) of the tumor sections for expression of P-gp, HIF-1α, EGFR, HXK2, CD-31, and Stem Cell Factor (SCF) was used to assess the MDR character of the tumors after treatment." (PMID 21931642, 2011). "Gefitinib treatment did not alter the number of EGFR or HER2 expressed in tumor cell lines A431, U343, SKOV3 and SKBR3." (PMID 21931838, 2011). "However, in our study, the positivity of COX-2 in tumor was as high as 90%, and the number of cases was too small to analyze survival with further stratification between COX-2 and EGFR positive patients." (PMID 21385353, 2011). "By targeting the EGFR-dependent cancer cell proliferation and the VEGFR-2-dependent tumour angiogenesis pathways, vandetanib offers the potential advantages of blocking two key pathways in different tumour types, namely cell proliferation and angiogenesis." (PMID 21970874, 2011). "One third of the patients with wt-KRAS or mt-BRAF tumour still respond to the treatment ̧ alluding that the BRAF status is not predictive for the response to anti-EGFR antibody therapy." (PMID 22933967, 2011). "Based on the COX proportional hazard analysis adjusting for other significant variables, the mortality of patients with positive tumor EGFR expression was 2.31 times that of the EGFR negative NSCLC (P < 0.05)." (PMID 21385353, 2011). "In the biomarker analysis of the SATURN trial, patients derived a PFS benefit with erlotinib irrespective of EGFR FISH status in their tumours." (PMID 21654681, 2011). "The result of histological heterogeneous staining suggests that phosphorylation of the EGFR pathway components do not occur in a synchronized manner within the tumor." (PMID 21554739, 2011). "Lack of EGFR protein expression was observed in nine EGFR promoter methylated tumours (30%) and in seven EGFR promoter unmethylated tumours (32%)." (PMID 21559018, 2011). "A Kirsten ras sarcoma viral oncogene (KRAS) wild-type (WT) status of the tumor is necessary, but possibly not sufficient, for a response to anti-EGFR monoclonal antibody therapy." (PMID 21437184, 2011).
tumor (continued). "Nevertheless, even among patients with KRAS wild-type tumours, the majority of patients do not respond to anti-EGFR therapy." (PMID 21364579, 2011). "Most participants would not request additional tumour analyses (e.g. epidermal growth factor receptor (EGFR), cytokeratin 5/6, 14 and 17)." (PMID 22276059, 2011). "EGFR represents a rational target for anti-tumor strategies, however anti-EGFR agents have shown no effective response in HCC patients." (PMID 24212818, 2011). "To evaluate whether there were any differences in the EGFR/MAPK signaling between cetuximab treatment (+) and (-) in vivo, we measured the total EGFR, phosphor-EGFR, and phosphor-ERK staining in the xenograft tumor sections." (PMID 21554739, 2011). "While the present trial requires that parameters of the EGFR-pathway are determined, KRAS mutation of the tumour does not affect treatment within the trial." (PMID 21861888, 2011). "Given that both EGFR and PTGS2 (COX-2) pathways orchestrate to promote tumor initiation, progression, angiogenesis, and metastasis, it is conceivable that combined targeting to both PTGS2 (COX-2) and EGFR pathways will yield better clinical outcome in CRC prevention and treatment." (PMID 24213116, 2011). "In order to evaluate the EGFR and COX-2 expression and their impact on prognosis of NSCLC patients receiving post-operative adjuvant therapy, the paraffin embedded tumor samples from 50 NSCLC were analyzed immunohistochemically for EGFR and COX-2 expression and their prognostic values were explored." (PMID 21385353, 2011). "The immunohistochemical analysis of KL-6 using three postmortem autopsy specimens showed that KL-6 was expressed at tumor cells in the primary lesions as well as alveolar epithelial cells in the EGFR-TKIs induced ILDs (data not shown)." (PMID 21791074, 2011). "It seemed likely that the function of LIV-1 was to stimulate the expression of MMP2, MMP9 and HB-EGF proteins, which in turn activated EGFR and downstream ERK signaling, leading to EMT that facilitated local tumor growth and its distant metastases to bone and soft tissues." (PMID 22110740, 2011). "In this study, 46 carcinomas showed EGFR gene amplification, which include 42 tumors (30.2%) presenting high polysomy and 4 tumors (2.9%) presenting amplification (based on the ratio of EGFR gene copies to CEP7 gene copies in at least 100 tumor cell nuclei)." (PMID 22132735, 2011). "Tumor growth inhibition induced by a single dose of AST1306 in the SK-OV-3 xenograft model was accompanied by a rapid (within 2 h) and sustained (≥24 h) inhibition of both EGFR and ErbB2, consistent with an irreversible inhibition mechanism." (PMID 21789172, 2011). "While the activation of EGFR and Her-2 on the cell surface of the head and neck tumors has proven to lead to tumor growth, these are not necessarily expressed in altered levels, nor released into the saliva of OSCC patients." (PMID 20429940, 2010). "We also analysed EGFR as a dichotomised variable and compared tumours with absent/weak/moderate EGFR intensity (0, 1+, and 2+) vs strong (3+) staining." (PMID 19997103, 2010). "EGFR was dramatically overexpressed in CSQT-2 cells, which may contribute to the rapid tumour growth." (PMID 20461085, 2010). "Absent/weak/moderate EGFR intensity (0, 1+, and 2+) was detected in 301 (83%) tumours and complete strong circumferential staining (3+) was found in 60 (17%)." (PMID 19997103, 2010). "In non hepatic epithelial tumor cell lines, inhibition of EGFR or IGF-1R individually promotes activation of the reciprocal receptor and IGF-2 overexpression has been involved in the resistance of HCC to EGFR inhibition in a rat model." (PMID 20860815, 2010). "We recently revealed that p37 promoted tumor cell motility, migration and invasion in vitro and enhanced tumor cell metastasis in C57BL/6 mice, which was mainly mediated by matrix metalloproteinase-2 (MMP-2) and the EGFR/MEK/ERK pathway." (PMID 21062494, 2010).
tumor (continued). "EGFR targeting in HRPC is a logical approach as HER1 is very frequently overexpressed in this disease, and activation of EGFR leads to cell proliferation, neoangiogenesis, and an increasedtumor invasion due tothe greater mobility of these tumor cells." (PMID 27713352, 2010). "Indeed, ATII through AT1-R can activate tumour cell proliferation through at least two simultaneous mechanisms: PI3-kinase/Akt pathway and EGFR (epithelial growth factor receptor) trans-activation." (PMID 21102591, 2010). "EGFR protein, as assessed by immunohistochemistry, was overexpressed in 76% of tumours (data not shown) and did not correlate with response to cetuximab as previously demonstrated in other studies." (PMID 20234366, 2010). "An immortalized thyrocyte cell line, N-Thy-ori3-1, and the HeLa cell line were included as controls for EGFR-expressing nontransformed and tumor cells, respectively." (PMID 20877637, 2010). "Unfortunately, not all patients bearing tumours with over-expression of EGFR or Her2 respond to those drugs." (PMID 21176167, 2010). "No patient with an EGFR gene copy number below 2.47 had a tumor response, while six of 20 patients with an EGFR gene copy number above 2.47 had an objective response (p = 0.0009)." (PMID 20680105, 2010). "As EGFR, PTEN and MGMT genes are usually altered in primary GBMs, we decided to corroborate the primary nature of our samples by checking for the existence of these alterations in the bulk tumour cell population of GBMs by FISH analysis and MLPA assay." (PMID 20735813, 2010). "We investigated whether AEE788 (a combined inhibitor of EGFR, HER2 and VEGFR) plus tamoxifen or letrozole enhanced the individual anti-tumour effects of these agents." (PMID 20386540, 2010). "Noteworthy, EGFR staining was seen mainly in the periphery of the tumor where there was contact with non-neoplastic brain parenchyma." (PMID 20604919, 2010). "Response rates in patients that do not harbor an activating mutation in EGFR are low, and mutations in KRAS and EGFR rarely occur in the same tumor." (PMID 20591134, 2010). "EGFR mediated PI3K/Akt activation promotes β-catenin transactivation and tumor cell invasion, suggesting that EGFR activation transactivate β-catenin activity via receptor tyrosine kinase pathways in tumor cells." (PMID 20828404, 2010). "The EGFR protein expression had a significant correlation with the histological grade of the tumours but not with the outcome of the patients." (PMID 20664595, 2010). "To date, it has been demonstrated that the tumor EGFR expression detected by IHC does not represent a good predictive marker of response to Cetuximab." (PMID 20398370, 2010). "There was a significant correlation between the EGFR protein expression and the histological grade of the tumours, but not with the clinical outcome of the patients." (PMID 20664595, 2010). "Patients with chemorefractory mCRC and low (< 1%) or negative (1% to 9%) EGFR tumor cell expression were treated with panitumumab 6 mg/kg every two weeks until disease progression or intolerability." (PMID 20680105, 2010). "We found that captured CTCs were amenable to quantitative IF scoring for both EGFR and HER2 on the standard CellSearch® platform, and that the levels of spiked tumor cells isolated from blood were generally reflective of expression levels in the parent cell line." (PMID 20838621, 2010). "The antitumor activity of vandetanib against EGFR may therefore reduce the levels of VEGF and other growth factors released by tumor cells." (PMID 21050422, 2010). "However, tumors expressing EGFR-L858R or having the TGFα autocrine production were considerably resistant to MET silencing, as demonstrated by a complete rescue in tumor incidence." (PMID 20500904, 2010). "Not surprisingly, since cell proliferation is necessary for tumor promotion, EGFR signaling plays an important role in skin carcinogenesis." (PMID 21297902, 2010).
tumor (continued). "The expression of EGFR -L858R or TGFα does not significantly promote tumor growth in untreated cells (expressing MET)." (PMID 20500904, 2010). "Upon treatment of RT2 mice with EGFR inhibitors, PNET tumors harboring wild-type, nonamplified alleles of Egfr grow at a markedly reduced rate and display a significant increase in tumor cell apoptosis, as well as reduced neovascularization." (PMID 20975924, 2010). "In conclusion, these data show that inhibition of both the VEGF and EGFR pathways demonstrates efficacy in NSCLC xenografts and that combining such agents with radiation could improve the anti-tumour activity of radiation alone." (PMID 20628392, 2010). "Overall, EGFR, p-AKT and p-ERK expression was detected in 37, 24 and 13% of tumour specimens." (PMID 20683448, 2010). "In conclusion, our data show that EGFR GCN and KRAS mutation status are neither predictive nor prognostic factors for pathological tumour response and DFS in LARC patients treated with preoperative chemoradiation." (PMID 20842128, 2010). "PTEN is a key tumor suppressor that inactivates PI3K, a downstream effector of the EGFR cascade." (PMID 20680105, 2010). "In many studies, biopsy samples obtained at the time of primary surgery are used to characterise EGFR levels but the molecular characteristics of the tumour after recurrence are not always the same." (PMID 20515495, 2010). "Although we do not know whether the high expression of EGFR signal is promoted by versican or activitated in association with other molecular determinants, understanding the signaling cascade is important towards the mechanisms of action in factors that influence tumor invasiveness." (PMID 21079779, 2010). "The patients were only represented once in this study; that is, the same tumor was not examined for EGFR expression upon recurrence." (PMID 20509969, 2010). "As selective EGFR inhibitor AG 1478 blocked G3 effects on tumor cell migration while MEK inhibitor PD 98059 did not suggest that ERK was the main downstream signaling component when specifically considering effects on cell migration." (PMID 21079779, 2010). "It appears that tumors of the distal esophagus and gastroesophageal junction (GEJ) may be more sensitive to EGFR blockade than distal gastric adenocarcinomas." (PMID 19636422, 2009). "A second small-molecule EGFR tyrosine kinase inhibitor, erlotinib, was also found to have anti-tumor activity in phase II trials, but, unlike gefitinib, demonstrated improved survival in a placebo controlled phase III study." (PMID 19159467, 2009). "Growth factor receptors including EGFR and IGF1R are often overexpressed in tumor cells." (PMID 19323821, 2009). "In this study, we evaluated the ability of ZD4190, an orally available inhibitor of the vascular endothelial cell growth factor receptor 2 (VEGFR2) and of epidermal growth factor receptor (EGFR) signalling, to block the development of vasculature required to support outgrowth of tumour cells." (PMID 19623179, 2009). "The availability of this dataset allowed us to determine whether the GEPR could predict response to alternate EGFR-targeted agents, employ the use of KRAS status to enrich the predictive power, and function across tumor types (CRC versus non-small cell lung)." (PMID 19439077, 2009). "ErbB3 expression was also similar between the two groups, suggesting that p190B deficiency does not inhibit Neu-induced tumorigenesis by altering the epidermal growth factor receptor signaling axis that promotes tumor formation in this model." (PMID 19703301, 2009). "There were no objective responses, however, 1/5 of patients exhibited stable disease, and tumour response was not correlated with EGFR immunohistochemistry levels." (PMID 19563658, 2009). "Treatments are selected largely without regard for tumour mutation profiles, although recent evidence linking KRAS mutation with poor response to EGFR mAb now influences decisions in the clinic." (PMID 19603024, 2009).
tumor (continued). "As VEGFR-2 was not expressed in both cells, direct anti-tumour effect of vandetanib in this study was anti-EGFR inhibition, and anti-VEGFR-2 inhibition of vandetanib was exerted in the tumour stroma." (PMID 19319137, 2009). "Such inhibition was not apparent for tumours treated with radiation alone, suggesting a rationale for combined treatment with anti-EGFR mAbs and radiotherapy." (PMID 19293809, 2009). "Although tyrosine kinase receptors, such as EGFR, are capable of activating STAT3, the incidence of STAT3 activation by inflammatory cytokines (such IL-6) in cooperation with EGFR is common among some tumours." (PMID 19088723, 2009). "The epidermal growth factor receptor (EGFR) expression was studied by the authors of the current study in nearly 80% of the patients and almost all the patients had documented expression of EGFR in the tumor cells." (PMID 20838543, 2009). "The studies of erlotinib and gefitinib identified a population that is more likely to respond to anti-EGFR therapy, i.e. never-smokers, of Asian heritage, female sex, and a tumor with adenocarcinoma histology." (PMID 19159467, 2009). "Panitumumab has a moderate activity in primary and metastatic colorectal carcinoma with no evident correlation with tumor EGFR expression." (PMID 18991714, 2008). "In addition, MdOS also targeted HER-2, EGFR, FGFR and PDGFR that are directly or indirectly involved in tumor angiogenesis." (PMID 19020661, 2008). "Similarly, EGFR and VEGF expressions were significantly higher in high stage tumours than low stage tumours (p = 0.03 and p = 0.04, respectively)." (PMID 19014499, 2008). "Additionally we selected seven other genes, ATF3, ADAMTS1, EGFR, PRNP, IGFBP6, ID4 and FN1, found to be differentially expressed according to tumor subtype and ER+/ER- classification from the tumor-specific differentially expressed gene-set." (PMID 19116033, 2008). "The odds of complete response were 12.8 for VEGF-negative and EGFR-positive tumours compared with VEGF-positive and EGFR-negative tumours." (PMID 18182986, 2008). "A single copy of chromosome 9, 13, 15, 18 and 22 was found in at least one EGFR tumor, no monosomy was found in the KRAS group." (PMID 18549475, 2008). "Five-year survival for patients with EGFR-positive and EGFR-negative tumours was 17.7 and 47.1% for IHCC, and 26.4 and 45.6% for EHCC, respectively." (PMID 18087285, 2008). "Interestingly, although EGFR inhibition induces a VEGF reduction in both protein extracts and conditioned media of wild-type tumour cells, only everolimus efficiently inhibits VEGF levels in EGFR inhibitor-resistant cells." (PMID 18319715, 2008). "Therefore, we analyzed the EGFR and STAT3 proteins in the A2780 cDDP tumor xenografts from mice treated with NCX-4040 and/or cisplatin." (PMID 18302761, 2008). "Combining IgG1 EGFR-antibodies recognizing different, non-overlapping epitopes, however, resulted in potent complement activation and effective lysis of tumor cells." (PMID 18702090, 2008). "Copy number changes relative to the Line-1 gene and the calibrator were determined by the formula (TEGFR/TLine-1)/(CEGFR/CLine-1), where TEGFR/TLine-1 are quantity from tumor DNA by using EGFR and Line-1, and CEGFR/CLine-1 are quantity from calibrator by using EGFR and Line-1." (PMID 18950515, 2008). "However, the combined inhibition of EGFR, Akt, and mTOR after EGCG+tamoxifen treatment provides a powerful suppression of tumour growth." (PMID 18797454, 2008). "Supervised analysis of gene expression profiling ofMPNSTs revealed that EGFR-positiveand -negative tumours had a specific gene expression signatures." (PMID 18769552, 2008). "We also observed that EGFR-positive/pEGFR-positive tumours had worse prognosis in contrast to EGFR-negative and/or pEGFR-negative ones." (PMID 18522728, 2008).